TNF (tumor necrosis factor)
Diseases named in the same sentence as TNF in open-access papers (continued):
Sharing a sentence is not in itself a finding about the gene and the disease.
hepatitis B (continued). "The results indicated that pathways in cancer, hepatitis B, and the TNF signaling pathway were the significantly enriched pathways of Xihuang pill on the TNBC stem cells." (PMID 34737698, 2021). "After KEGG pathway enrichment, we found that cluster 1 was enriched in the hepatitis B and TNF signaling pathway, cluster 2 was enriched in the apoptosis and hepatitis B pathway, and cluster 3 was enriched in the peroxisome pathway." (PMID 33747110, 2021). "In hPLF-hTERT, this gene is related to different pathways pointed out by KEGG, such as epithelial cell signaling in Helicobacter pylori infection, pertussis, hepatitis B, TNF signaling pathway, and NOD-like receptor signaling pathway." (PMID 34141725, 2021). "From the visual results of the first 10 pathways, the target gene of the main signaling pathways of prescription was concentrated in pathways in the IL−17 signaling pathway, Th17 cell differentiation, TNF signaling pathway, Hepatitis B, etc.." (PMID 35127768, 2021). "Our results showed that NFKB in CD8+ T cells participates in 11 signal pathways, including the TNF signaling pathway, apoptosis signaling pathway, and hepatitis B signaling pathway." (PMID 34880858, 2021). "The core targets of plantain for hyperuricemia are RELA, MAPK1, NFKBIA, CASP3, CASP8, and TNF, and the main pathways are pathways in cancer, apoptosis, hepatitis B, IL-17 signaling pathway, and toxoplasmosis." (PMID 33149752, 2020). "There are 31 intersection targets for hyperuricemia, the main targets are RELA, MAPK1, NFKBIA, CASP3, CASP8, and TNF, and the main pathways include pathways in cancer, apoptosis, hepatitis B, IL-17 signaling pathway, and toxoplasmosis." (PMID 33149752, 2020). "The pathway with the most enriched genes is the cancer pathway, with 12 genes; followed by the TNF signaling pathway, hepatitis B pathway, apoptotic pathway, NF-kappa B signaling pathway." (PMID 32293395, 2020). "In the KEGG pathway enrichment analysis, both of these two datasets were mainly enriched in TNF signaling pathway, influenza A, Toll-like receptor signaling pathway, herpes simplex infection, measles, legionellosis, and hepatitis B." (PMID 33330617, 2020). "Reactivation of infections such as tuberculosis and hepatitis B by administering anti-TNF agents has been reported." (PMID 29429045, 2018). "A similar phenomenon is seen in B hepatitis, where secretion of TNF-α by macrophages and infected hepatocytes contributes to liver cell death." (PMID 24490832, 2014). "A number of clinical studies cumulatively show that serum levels of IL-1 and TNFα are increased in hepatitis B patients." (PMID 24025329, 2013). "In this study, levels of plasma α2-Heremans-Schmid glycoprotein, serum tumor necrosis factor-α, serum liver function parameters and short-term mortality were measured in 100 hepatitis B patients." (PMID 21747711, 2011). "Further kyoto encyclopedia of genes and genomes (KEGG) pathway analysis of the target genes revealed that they were primarily enriched in the IL-17 signaling pathway, TNF signaling pathway, FoxO signaling pathway, Alcoholic liver disease pathway, Hepatitis B pathway, and Chemokine signaling pathway." (PMID 41362732, 2026). "TNF-α inhibitors were excluded over safety concerns in hepatitis B and malignancy." (PMID 41142781, 2025). "In the KEGG analysis, enrichment was found for pathways related to the MAPK signaling pathway, measles, hepatitis C, human cytomegalovirus infection, cancer pathways, the TNF signaling pathway, hepatitis B, influenza A, Epstein–Barr virus infection, and human papillomavirus infection, among others." (PMID 39000042, 2024). "IFN- γ and TNF-α play a critical role in the management of hepatitis B virus infections." (PMID 39328404, 2024).
hepatitis B (continued). "It results displayed that the therapeutic effect of TanIIA on HCC may be achieved through MAPK, Transcriptional misregulation, Hepatitis B, TNF, endocrine resistance and other signaling pathways." (PMID 39544939, 2024). "It is worth noting that the use of anti-TNF agents (mainly certolizumab and infliximab), male gender and vaccination for hepatitis B after starting treatment with anti-TNF are risk factors for non-response to this vaccine." (PMID 38238209, 2024). "We found that the mechanisms of GXZY may be related to the pathways in cancer, hepatitis B, TNF signaling pathway, and MAPK signaling pathway derived from network pharmacology analysis." (PMID 35330838, 2022). "Its mechanisms could be related to reducing the expression of MMP9, and pathways such as pathways in cancer, hepatitis B, TNF signaling pathway, and MAPK signaling pathway." (PMID 35330838, 2022). "In addition, J774A.1 macrophages treated by the codelivery system were successfully differentiated into the M1 phenotype and expressed enhanced cytokines with anti-hepatitis B effects such as interleukin 6 (IL-6) and tumor necrosis factor-α (TNF-α)." (PMID 35890334, 2022). "Previous studies also revealed the risk of HBVr in patients with CHB after therapy with TNF-alpha inhibitors such as infliximab, supporting the role of TNF-alpha in viral replication suppression and the warrant of hepatitis B serological marker testing before the initiation of anti-TNF therapy." (PMID 35163330, 2022). "Its mechanism may related to multiple therapeutic targets and signaling pathways such as cancer pathway, hepatitis B, and TNF signaling pathway." (PMID 36626454, 2022). "Furthermore, these key genes were related to pathways in cancer, hepatitis B, TNF signaling pathway, and MAPK signaling pathway." (PMID 35330838, 2022). "Similarly, network analysis of switch genes from females in dataset GSE112681 was enriched in ribosome biogenesis, TNF signaling, hepatitis B and C, apoptosis, protein processing in the endoplasmic reticulum, IL-17 signaling, and others." (PMID 34281203, 2021). "Ranked according to the p-value, the top five pathways were pathways in cancer (p = 5.42E−32), AGE-RAGE signaling pathway in diabetic complications (p = 2.65E−29), TNF signaling pathway (p = 5.85E−18), IL-17 signaling pathway (p = 1.04E−17), and hepatitis B (p = 1.04E−17)." (PMID 34868222, 2021). "Additionally, the outcomes of the KEGG enrichment analysis show that the candidate targets were mainly enriched pathways in cancer, hepatitis B, and the TNF signaling pathway." (PMID 34737698, 2021). "From the results of the present study, based on the KEGG enrichment analysis, the potential pathways of JDNW Formula in the treatment of ACLF were closely related to pathways in cancer, hepatitis B, TNF signaling pathway, cAMP signaling pathway, AMPK signaling pathway, and calcium signaling pathway." (PMID 33456481, 2020). "Therefore, in the next paragraph we provide practical recommendations for the proper management of patients with positive markers of hepatitis B or C receiving anti-TNF-α agents as a treatment." (PMID 30060508, 2018). "Anti-TNFα treatments are likely to be safe in patients with past hepatitis B serological pattern." (PMID 19941642, 2009). "Flavonoids could modulate apoptosis by targeting Casp3 in the infection process of pertussis, legionellosis, amoebiasis, toxoplasmosis and hepatitis B. In addition, during the subsequent inflammation process followed by infection, flavonoids could regulate inflammation through TNF-alpha." (PMID 27023590, 2016). "Abnormal expression of TNF-α, CRP and IL-6 inflammatory markers can promote liver inflammation, fibrosis and damage and aggravate liver function damage and disease severity of hepatitis B complicated with alcoholic cirrhosis." (PMID 41281287, 2025).
hepatitis B (continued). "In contrast, the genes with downregulated expression were mainly enriched in alcoholism, hepatitis B, neutrophil extracellular trap formation, as well as NOD-like receptor, RIG-I-like receptor, TNF, and Toll-like receptor signaling pathways." (PMID 39679172, 2024). "The KEGG analysis mainly contained pathways in cancer, hepatitis B, AGE-RAGE in diabetic complications, PI3K-Akt, IL-17, and TNF signalling pathway." (PMID 36330452, 2022). "Meanwhile, these targets were significantly involved in PI3K-Akt signaling pathway, TNF signaling pathway, AGE-RAGE signaling pathway, hepatitis B, and pathways in cancer through GO and KEGG enrichment analysis." (PMID 35837376, 2022). "Obviously, the data showed that EH mainly regulated pathways in cancer, hepatitis B, PI3K-Akt signaling pathway, HTLV-I infection, and TNF signaling pathway to treat NS." (PMID 35837376, 2022). "KEGG enrichment analysis revealed pathways in cancer, toxoplasmosis, hepatitis B, HIF-1 signaling pathway, T cell receptor signaling pathway, toll-like receptor signaling pathway, TNF signaling pathway, and others." (PMID 34567206, 2021). "The results showed that a total of 103 common genes shared by CS and liver cancer were obtained, which were enriched for precancerous lesion pathways such as hepatitis B and fatty liver and biological signaling pathways such as HIF-1 and TNF." (PMID 33294448, 2020). "After hepatitis B infection in chimpanzees, CD8+ T cells secreted IFN-γ and TNF-α to halt viral replication and reduce viral loads in hepatocytes." (PMID 33007914, 2020). "Our result showed that JUN was involved in Hepatitis B, NOD-like receptor signaling pathway, AGE-RAGE signaling pathway in diabetic complications, Pathways in cancer, IL-17 signaling pathway, TNF signaling pathway." (PMID 31138194, 2019). "The risks of hepatitis B (HR = 4.3, 95% CI: 1.5–12.7) and TB (HR = 5.1, 95% CI: 2.0–13.6) reactivation also increased for patients with IBD who were treated with anti-TNF-α, especially among those in the high accumulated dosage group." (PMID 30373275, 2018). "Regarding hepatitis B infection, CD8T cells producing interferon gamma and tumor necrosis factor (TNF)-α may influence regulatory T lymphocytes, altering the Th1/Th2 balance." (PMID 40191527, 2025). "Additionally, the response rate to certain vaccines, such as hepatitis B, is often low in IBD patients on immunosuppressors or anti-TNF therapy." (PMID 39200937, 2024). "Our results showed that EH could be applied in the treatment of NS through PI3K-Akt signaling pathway, TNF signaling pathway, AGE-RAGE signaling pathway, hepatitis B, and pathways in cancer." (PMID 35837376, 2022). "Moreover, IFN-γ and TNF-α level in the supernatant was significantly higher in CD8+ T cells from NC compared with CHB and hepatitis B-related HCC patients (P<0.0001, SNK-q tests)." (PMID 34177894, 2021). "In general, cytotoxic mechanisms for HBV-specific CD4+ and CD8+ T cells and noncytotoxic mechanisms for IFN-γ and TNF-α, which are produced by natural killer (NK) cells, are detectable in acute hepatitis B patients." (PMID 33670625, 2021). "KEGG analysis showed that CCMMs may produce anti-PLC effects via multiple pathways, including pathways in cancer, hepatitis B, PI3K-Akt, TNF, MAPK, hepatitis C, HIF-1, toll-like receptor, and Ras signaling pathway." (PMID 32382293, 2020). "Correlations between anti-TNF-α agents and increased risks of serious infection (non-gastrointestinal bacterial infection requiring hospitalization), and TB and hepatitis B reactivation have been reported." (PMID 30373275, 2018).
hepatitis B (continued). "In the present study, 289 of 1693 patients [17.1%] did not have any hepatitis B tests, but 230 of them had a history of anti-TNFα therapy for which hepatitis B screening is strongly recommended." (PMID 26961546, 2016). "Although the main producer cells of these cytokines in hepatitis B patients are not defined, it has been reported that the secretion of IL-1 and TNFα in nonparenchymal cells were increased by HBV infection into hepatocytes." (PMID 24025329, 2013). "Fundamental studies have found that hepatitis B virus infection could increase the production of tumor necrosis factor (TNF), especially in HBeAg-negative patients." (PMID 34497643, 2021). "Therefore, it is critical to confirm the absence of latent tuberculosis and hepatitis B virus infection prior to starting anti-TNF therapy." (PMID 29429045, 2018). "In contrast to the response observed after infection, the majority of vaccine-induced CD4+ T cells had a phenotype of IL-2+TNF-α+IFN-γ- cells similar to responses observed with other non-live vaccines, such as hepatitis B or tetanus." (PMID 26465323, 2015). "Some reports and a meta-analysis suggest that several non-live inactivated vaccines (hepatitis A, hepatitis B, influenza, and Streptococcus pneumoniae) may not elicit adequate seroprotection when administered to adult IBD patients treated with anti-TNF agents." (PMID 39200937, 2024). "However, there were no remarkable differences of secreted IFN-γ or TNF-α by CD8+ T cells between CHB and hepatitis B-related HCC patients (P>0.05, SNK-q tests)." (PMID 34177894, 2021). "The top 13 (Count Number ≥ 12) pathways included cancer, hepatitis B, PI3K-AKT, neuroactive ligand-receptor interactions, HTLV-I infection, TNF, influenza A, cAMP, proteoglycans in cancer, MAPK, non-alcoholic fatty liver disease, viral carcinogenesis and microRNAs in cancer signaling pathways." (PMID 32450873, 2020).
renal fibrosis (169 papers, 2014 to 2026). A final common manifestation of a wide variety of chronic kidney diseases characterized by glomerulosclerosis and tubulointerstitial fibrosis. "We also demonstrated that angiotensin II and TNF, two factors implicated in the pathogenesis of renal fibrosis in the UUO model, can induce CypA secretion by cultured WT tubular epithelial cells." (PMID 32455976, 2020). "M1 macrophages release inflammatory mediators including ROS and TNFα, which augment an injury in a positive feedback loop, to cause renal fibrosis." (PMID 31360120, 2019). "In the early stages of UUO, the pro-inflammatory macrophage (M1) is the predominant macrophage phenotype, directly inducing renal fibrosis by releasing pathogenic mediators such as TNF-α, IL-1β, CCL2 and reactive oxygen species (ROS)." (PMID 28416741, 2017). "The homing of inflammatory macrophages to renal tissues has been identified as a potent mechanism in fibrosis progression, and macrophage-derived factor TNFα has been shown to be a key pathogenic regulator of UUO-induced renal fibrosis." (PMID 27454431, 2016). "TNF causes renal fibrosis by excessive deposition of extracellular matrix." (PMID 40909020, 2025). "As CKD fibrosis progresses, senescent cells express and secrete pro-fibrotic factors (TGF-β, CTGF, and so forth) and pro-inflammatory factors (IL-1β, IL-6, TNF-α, and so forth), which are senescence-associated secretory phenotype factors, thereby accelerating renal fibrosis." (PMID 35227255, 2022). "It significantly reduced cardiac and renal fibrosis and suppressed the expression of pro-inflammatory (IL-1β, TNF-α), pro-fibrotic (Col1A1, α-SMA), and cardiac stress (BNP, ET-1, ANF) markers." (PMID 41596359, 2026). "TNF-α also contributes to renal fibrosis, characterized by excessive accumulation of extracellular matrix proteins, which leads to scarring and loss of kidney function." (PMID 39744177, 2025). "This modulation improves intestinal barrier function, reduces pro-inflammatory cytokines such as TNF-α and IL-6, and effectively alleviates renal fibrosis." (PMID 41048436, 2025). "M1 macrophages, prevalent in DN, initiate inflammation, tissue damage, and renal fibrosis via proinflammatory cytokines such as TNF-a, IL-6, IL-10, and monocyte chemoattractant protein 1 (MCP-1)." (PMID 41438111, 2025). "TNF expression in IgAN patients is higher than among normal people, and its activation is closely related to renal fibrosis." (PMID 39492771, 2025). "Adipocytes secrete inflammatory mediators such as tumor necrosis factor-α (TNF-α) and interleukin-6 (IL-6), which contribute to the irreversible progression of renal fibrosis." (PMID 41424782, 2025). "More recently, involvement of TNF-α in renal fibrosis, as well as the benefits of its inhibition have been described in murine aristolochic acid-induced nephropathy (considered superior to previously employed murine models)." (PMID 39469576, 2024). "In conclusion, we showed that TMAO can enhance TNF-α mediated renal fibrosis and release of inflammatory mediators from renal fibroblasts in vitro." (PMID 38643262, 2024). "While not specifically implicated in S-AKI, NR5A2 regulates the calreticulin gene during renal fibrosis and plays a role in multiple immune pathways including inflammation and tumor-necrosis factor- (TNF) induced cell death." (PMID 39636799, 2024). "For example, elevated levels of tumor necrosis factor-alpha (TNF-α) and interleukin-6 (IL-6) are closely associated with renal fibrosis, renal function decline, and the occurrence of albuminuria." (PMID 39491271, 2024). "Our study is the first aiming to elucidate the combined effect of TMAO and TNF-α on renal fibroblasts through assessing aspects of renal fibrosis and inflammation." (PMID 38643262, 2024). "Utilizing single-cell transcriptomics, TNF from activated leukocytes drove Gli1+ cell proliferation and fostered renal fibrosis by elevating Indian Hedgehog (IHH) release from TECs." (PMID 38770013, 2024).